SPHK1 (sphingosine kinase 1)
Diseases named in the same sentence as SPHK1 in open-access papers (continued):
Sharing a sentence is not in itself a finding about the gene and the disease.
preeclampsia (7 papers, 2016 to 2025). Preeclampsia is a hypertensive disorder of pregnancy that is characterized by new-onset hypertension with proteinuria presenting after 20 weeks of gestation, and depending on mild or severe forms may initially present with severe headache, visual disturbances, and hyperreflexia. "Preeclampsia was associated with significant decrease of placental SPHK1 gene expression (p = 0.025)." (PMID 27284992, 2016). "One limitation of our study is that we evaluated term placentae, but would be of great interest to determine SPHK1 expression pattern in 1st trimester human placentae in patients at risk of developing preeclampsia by using intrauterine artery Doppler as a predictive factor." (PMID 27284992, 2016). "The causes of down-regulation of SPHK1 observed during preeclampsia are unknown." (PMID 27284992, 2016). "Evidently, the exact mechanism(s) by which HIF1 regulates SPHK1 expression during placental development and preeclampsia warrants further investigation." (PMID 41167398, 2025). "In preeclampsia, it is possible that decreased SPHK1 levels lead to persistent HIF1A stabilization and activity." (PMID 27284992, 2016). "In the present study, we demonstrate for the first time that the SPHK1/S1P receptor pathway is impaired in placentae of preeclamptic patients and in term placental villous explants of severe preeclampsia when compared to controls." (PMID 27284992, 2016). "SPHK1 was downregulated in term placentae and term chorionic villous explants from patients with preeclampsia, suggesting a role of SPHK1 in trophoblast cell functions and preeclampsia." (PMID 34262394, 2021). "This may indicate that SPHK1 and its product, sphingosine-1 phosphate might be an important angiogenic mediators during early placentation process, which is severely affected in preeclampsia." (PMID 27284992, 2016). "In this study, we hypothesized that angiogenic SPHK1/S1P pathway is impaired in preeclampsia." (PMID 27284992, 2016). "Indeed, our data demonstrated the reduction of SPHK1 mRNA and protein levels in term preeclamptic placentae and as well chorionic villous explants of severe preeclampsia when compared to the control subjects, confirming that SPHK1 is expressed not only by the whole placenta, but also fetal tissues." (PMID 27284992, 2016). "Results of the present study demonstrate impairment of SPHK1-S1P receptors pathway in human placentae and chorionic villous explants of PE patients, suggesting that it might be involved in challenged angiogenesis observed in preeclampsia." (PMID 27284992, 2016). "The SPHK1 promoter contains a HIF1A binding element and HIF1 is upregulated in human placentae at 5–9 weeks of gestation and in early-onset preeclampsia." (PMID 41167398, 2025). "Based on the literature, we hypothesized that the SPHK1-S1P pathway, previously well characterized angiogenic pathway involved in tumorigenesis and metastasis is down-regulated in pathological state such as preeclampsia, which is compromised by insufficient endometrial/placental vascularization." (PMID 27284992, 2016). "Collectively these data provide further support to the notion that SPHK1 and angiogenic S1PR1 and -3 receptors pathway is impaired in term human placentae from PE patients and might be responsible for impaired vasculogenesis/angiogenesis observed during preeclampsia." (PMID 27284992, 2016).
ulcerative colitis (7 papers, 2017 to 2025). An inflammatory bowel disease involving the mucosal surface of the large intestine and rectum. "Although very little is known regarding the extent to which oxidative stress impacts S1P metabolism, it has been reported that beneficial effects of the flavonoid resveratrol in experimental ulcerative colitis may be linked to its inhibitory effect on SphK1." (PMID 28300788, 2017). "Furthermore, an inhibition of S1P synthesis via the blockage of sphingosine-1-kinase enzymatic activity decreases the inflammatory response in septic mice, whereas SphK1 gene deficiency acts similarly with respect to the inflammation in the case of mice with severe ulcerative colitis." (PMID 29207545, 2017). "Two genes related to cellular metabolism (dipeptidase 1 (DPEP1) and sphingosine kinase 1 (SPHK1)) were found to be related to the PFOA-promoted formation of ulcerative colitis using our self-developed Metabolic Gene and Pathway Query software and Comparative Toxicogenomics Database (CTD)." (PMID 39722626, 2025). "However, only one study has attributed the anti-inflammatory properties of resveratrol in rats with ulcerative colitis induced by oxazolone to inhibition of SphK1, whose activity correlated with the disease activity index." (PMID 28300788, 2017).
lung diseases (6 papers, 2005 to 2022). "We proposed that the loss of S1P, regulated enzymatically via sphingosine kinases 1 and 2 (SphK1/2) and sphingosine lyase (SphL), is directly linked to maladaptive lung repair and premature/accelerated cellular senescence, and it plays a critical role in radiation-induced lung disease." (PMID 29186841, 2017). "Recent evidence implicates the involvement of the Hippo/Yes-associated protein (YAP) 1 pathway in lung diseases, including IPF, but its plausible link to the SPHK1/S1P signaling pathway is unclear." (PMID 32192225, 2020). "In conclusion, these findings all support a potential oncogenic role of the SPHK1/S1P axis in lung diseases, and understanding its carcinogenic mechanism may bring new insights into the treatment of NSCLC or other diseases." (PMID 36361531, 2022).
lung injury (6 papers, 2016 to 2025). "The results in the current study show that SphK1 plays a critical role in atorvastatin-mediated protective effects against high tidal volume ventilation-induced lung injury (VILI)." (PMID 34970075, 2021). "We hypothesize that Ks extracts may exert protective effects against APAP-induced acute liver injury by modulating the SPHK1/S1P/S1PR2/S1PR4 pathway and the Nrf2/Keap1 pathway, thereby mediating oxidative stress and inflammatory responses." (PMID 40811614, 2025). "Notably, we observed that SPHK1, S1PR3, and S1PR5 in the sphingolipid metabolism pathway could be potential therapeutic targets for the prevention of acute liver injury induced by APAP, as mediated by the Ks extract." (PMID 40811614, 2025).
Stroke (6 papers, 2014 to 2021). Sudden impairment of blood flow to a part of the brain due to occlusion or rupture of an artery to the brain. "Microglial activation and Sphk1 induction have been identified as a major cellular source of acute ischemic injury and neuroinflammation in stroke." (PMID 33602274, 2021). "Additional support for the importance of S1P signaling mechanisms relevant to stroke may come from studies on S1P itself and its biosynthetic enzymes, SPHK1 and SPHK2." (PMID 26576074, 2015). "SphK2, but not SphK1 has been shown to be upregulated by HP and isoflurane in the brain in a HIF-dependent manner and pharmacological inhibition and genetic deletion of SphK2 were shown to abrogate the protective effects of preconditioning in experimental stroke." (PMID 25309325, 2014).
anemia (5 papers, 2012 to 2025). A reduction in the number of red blood cells, the amount of hemoglobin, and/or the volume of packed red blood cells. "This current study has provided a potential mechanism for cancer-related anaemia and the first evidence that plasma S1P and erythrocyte SphK1 activity are the potential markers for the diagnosis, monitoring, and predicating for PCa mortality." (PMID 22315056, 2012). "We have identified erythrocytes as the major source of S1P in our patients and shown a highly significant downregulation of erythrocyte SphK1 activity in PCa patients compared with control counterparts, suggesting a mechanism for PCa-induced anaemia." (PMID 22315056, 2012). "They suggested that this might be due to the reduced activity of sphingosine kinase-1 (SphK1) in erythrocytes, potentially secondary to anemia in sPC or other sPC-related factors." (PMID 41375016, 2025).
Arthritis (5 papers, 2019 to 2022). Inflammation of a joint. "Accordingly, SPHK1-deficient mice showed decreased joint inflammation in a model of murine TNF-α-induced arthritis." (PMID 31379883, 2019). "Membrane targeting of SphK1 instead promoted the development of inflammatory M1 macrophages in a mouse model of collagen-induced arthritis." (PMID 36361636, 2022). "Sphingosine kinase (Sphk1) mediates TNFα-induced arthritis and osteoclastogenesis via TNFα receptor activating factor 2 (TRAF2)." (PMID 34968192, 2021). "Functional enrichment further supported that the primed genes are heavily involved in inflammatory response, arthritis-promoting functions (Ccl2, Cxcl5, Sphk1) and, interestingly, Wnt pathway (Bmp2, Rspo3, Cd44) and stem cell differentiation (Sox5, Nrp2, Cdk6)." (PMID 35879783, 2022). "In contrast, SPHK1-deficient mice were not protected from collagen-induced arthritis and thioglycollate-triggered peritonitis, indicating that SPHK1 activation may be restricted to specific inflammatory stimuli." (PMID 31379883, 2019). "By uncoupling the transcriptional cues with the unrealized epigenetic potential of the SFs, we also highlight genes such as Sphk1 and Pla2g2e, the targeting of which had been previously shown to ameliorate modeled TNF-mediated arthritis." (PMID 35879783, 2022).
Hepatic steatosis (5 papers, 2018 to 2023). Steatosis is a term used to denote lipid accumulation within hepatocytes. "S1P is suspected to increase lipid accumulation by activating S1PR2 and S1PR316, and knocking out Sphk1 protected from hepatic steatosis under a high-fat-high-glucose diet." (PMID 37953311, 2023). "Previous study showed that global Sphk1 depletion suppressed TG accumulation in liver and hepatic steatosis on diet-induced obese mice." (PMID 37751791, 2023). "Other studies have shown that SphK1 overexpression in obese mice promoted hepatic lipid accumulation, whereas its downregulation prevented hepatic steatosis." (PMID 37432552, 2023). "Firstly, hepatic steatosis is a risk factor for HCC and we, with others, have shown that deletion of SphK1 ameliorates hepatic steatosis." (PMID 29643998, 2018). "Lastly, a study showed that SphK1 expression increased in hepatic steatosis and that SphK1 KO mice were protected against hepatic steatosis induced by HFD, which supports the idea that endogenous S1P/SphK1 axis could be a major promoter of lipid accumulation in liver (steatosis)." (PMID 32668665, 2020).
Huntington disease (5 papers, 2019 to 2023). Huntington disease (HD) is a rare neurodegenerative disorder of the central nervous system characterized by unwanted choreatic movements, behavioral and psychiatric disturbances and dementia. "Sphk1 codes for sphingosine kinase 1, which is reported to promote protective autophagy of aggregated huntingtin proteins in Huntington’s disease." (PMID 36428550, 2022). "In addition, the protective effect of SphK1 was also found in Huntington disease (HD), a neurodegenerative disease with peripheral complications such as disturbance of gastrointestinal homeostasis." (PMID 34737701, 2021).
malaria (5 papers, 2019 to 2022). Malaria is a serious and sometimes fatal disease caused by a parasite that commonly infects a certain type of mosquito which feeds on humans. "Although increasing evidence suggests the involvement of S1P in malaria, very little is known regarding the role of SphK-1 and S1PR-3 in malaria-associated ALI/ARDS." (PMID 31483837, 2019). "Further studies should focus on the mechanism of particular cell types with increased expression of SphK1 and S1PR3 during pulmonary edema caused by malaria." (PMID 32185202, 2020). "First, the specimens used in this study were lung tissues from autopsied malaria patients that had been stored for approximately 30 years and were thus unsuitable for determining the gene expression levels of SphK-1 and S1PR-3 via molecular techniques." (PMID 32185202, 2020). "This depleted level of serum S1P can be correlated with reduced platelet count defining the possible role of S1P level in platelet formation, thus providing insights into the contribution of host-SphK-1 signaling in malaria pathogenesis." (PMID 32195246, 2020). "Toward this, we report for the first time that host-mediated SphK-1 level and its phosphorylation status decrease during malaria infection that could be the possible reasons underlying the reduced levels of S1P in the sera of malaria-infected patients, in line with the previous studies." (PMID 32195246, 2020). "The measurement of sphingosine and ceramide levels should be determined in the lung tissue and plasma samples to explain the functional role of SphK-1/S1P /S1PR-3 pathway involved in the pathogenesis of malaria." (PMID 31483837, 2019). "For immunohistochemistry staining, the lung tissues from malaria-infected mice with ALI/ARDS demonstrated intense cytoplasmic staining of SphK-1 in luminal endothelial cells of vascular blood vessels and alveolar epithelial cells." (PMID 31483837, 2019). "The present study showed enhanced SphK-1 expression in endothelial cells, alveolar epithelial cells and alveolar macrophages in the lung tissues of malaria-infected mice with ALI/ARDS." (PMID 31483837, 2019). "In addition, the current study demonstrated an increase in SphK1 in malaria-infected mice, which was consistent with previous reports on inflammatory conditions and cancer." (PMID 35333897, 2022). "Therefore, these proinflammatory cytokines can stimulate hepatocyte apoptosis, resulting in a decrease in S1PRs during SphK1 expression in malaria." (PMID 35333897, 2022). "In addition, the current study demonstrated that SphK-1 expression is substantially increased in pulmonary ECs, alveolar epithelial cells, and AMs in the lung tissues of malaria patients with PE." (PMID 32185202, 2020). "In an effort to determine the role of SphK-1 level and its phosphorylation in regulating the S1P levels during malaria parasite progression, we determined the relative levels of S1P in IC and EC milieu of the erythrocytes through LC/MS and ELISA-based analyses." (PMID 32195246, 2020). "In this study, there was a decrease in the S1P level, which might contribute to the reduction in the source of S1P in severe malaria, such as red blood cells and platelets; the location of S1P synthesis; and the duration of SphK-1 activation." (PMID 32185202, 2020). "Up to now it is clear that Sphk1/S1P signaling nexus and maintenance of adequate S1P level in erythrocytes is essential for intra-cellular parasitic growth, whereas low plasma S1P concentration contributes to severe manifestation of malaria." (PMID 32923406, 2020). "We hypothesized that S1P might mediate ALI/ARDS via a signalling pathway involving the conversion of sphingosine to S1P by SphK-1; then, binding of S1P to S1PR-3 leads to receptor activation that promotes the development of malaria-associated ALI/ARDS." (PMID 31483837, 2019).
malaria (continued). "Moreover, further studies of S1PR-3 antagonists/blockers in malaria-infected mice with ALI/ARDS would help to confirm the involvement of S1PR-3 and SphK-1 in malaria-infected mice with ALI/ARDS." (PMID 31483837, 2019). "Finally, to definitely demonstrate how SphK-1 and S1PR-3 are involved in malaria-associated ALI/ARDS, global gene expression analysis should be performed to identify the signalling pathways involved with SphK-1 and S1PR-3." (PMID 31483837, 2019). "Therefore, this study demonstrated that the elevated expression of the SphK-1 protein might be involved in vascular barrier regulation, leading to the development of PE in severe malaria." (PMID 32185202, 2020). "The present study indicated that liver tissue from malaria-infected mice has decreased expression of S1PR1, S1PR2, and S1PR3 and increased expression of SphK1." (PMID 35333897, 2022). "In conclusion, both the SphK-1 and S1PR-3 proteins were overexpressed in the lung tissues of severe P. falciparum malaria patients with PE, suggesting that SphK-1 and S1PR-3 mediate the pathogenesis of PE in severe malaria." (PMID 32185202, 2020). "Over expression of both SPHK-1 and S1PR-3 proteins were observed in lung tissues of PE indicating their role in the pathogenesis of pulmonary complications in severe malaria." (PMID 32923406, 2020). "A recent study revealed that the SphK-1 and S1PR-3 expression levels were significantly upregulated in the lung tissues of malaria-infected mice with ALI/ARDS." (PMID 32185202, 2020). "In malaria-infected mice with ALI/ARDS (n = 10), there was a positive correlation between the total score of SphK-1 and S1PR-3 expression levels in endothelial cells (Spearman’s rank correlation, rs = 0.997; p < 0.001)." (PMID 31483837, 2019). "Furthermore, increased expression of the SphK-1 and S1PR-3 proteins significantly correlated with lung injury scores and S1P concentrations in malaria-infected mice with ALI/ARDS." (PMID 31483837, 2019). "The results demonstrated that the cellular expression of the SphK-1 and S1PR-3 proteins was significantly upregulated in endothelial cells, alveolar epithelial cells and alveolar macrophages in the lung tissues of malaria-infected mice with ALI/ARDS compared with those in the control groups." (PMID 31483837, 2019).
oral squamous cell carcinoma (5 papers, 2020 to 2025). "The frequency of immunoreactivity score (IRS) of sphingosine kinase 1 (SphK1) and sphingosine kinase 2 (SphK2) has been calculated with different clinicopathological attributes of oral squamous cell carcinoma patients." (PMID 35494957, 2022). "SPHK1 promoted the progression and metastasis of oral squamous cell carcinoma via NF-κB-p65." (PMID 39875359, 2025).
papillary thyroid cancer (5 papers, 2013 to 2023). "The mRNA profiles of the papillary thyroid cancer cell line TPC1 with SPHK1 overexpression were further obtained by sequencing to assess the roles of SPHK1." (PMID 36050478, 2022). "In contrast, its ectopic upregulation suppresses tumor cell growth, migration, invasion, and EMT by targeting the 3′-UTR of SphK1 and SphK2 in the bladder and papillary thyroid cancers, respectively." (PMID 35201458, 2021). "59% (13 out of 22) and 60% (6 out of 10) of papillary thyroid cancer and follicular thyroid cancer, respectively, exhibited high SphK1 staining." (PMID 24970177, 2013). "The expression levels of miR-128 are remarkably downregulated in papillary thyroid cancer and follicular thyroid carcinoma tissues and cell lines, whereas its ectopic upregulation hampers tumor cell proliferation and invasion and induces cell cycle arrest and apoptosis by targeting SphK1." (PMID 35201458, 2021). "In contrast, not all papillary thyroid cancer and follicular thyroid cancer samples examined stained strongly for SphK1." (PMID 24970177, 2013).
squamous cell carcinoma (5 papers, 2015 to 2024). A carcinoma arising from squamous epithelial cells. "The role of miR124 has been resembled to a tumor suppressor gene which is mediated by inhibition of SPHK1 gene in squamous cell carcinoma." (PMID 39315290, 2024). "In the first study, AuNP nanorods (50–70 nm) were coated with siRNA against SphK1 (sphingosine kinase 1 gene) in a human squamous cell carcinoma xenograft." (PMID 39711799, 2024). "First, the Cancer Genome Atlas database (TCGA) validated that both in lung adenocarcinoma and squamous cell carcinoma (due to the lack of large cell carcinoma sample sizes, there is no corresponding database), the expression of SPHK1 in tumor tissues was notably up-regulated." (PMID 36361531, 2022).
allergic asthma (4 papers, 2016 to 2020). A asthma with a basis in a pathological type I hypersensitivity reaction. "In a model of allergic asthma it was shown that Sphk1 inhibition with a specific inhibitor decreased pulmonary inflammation." (PMID 27148053, 2016).